INS (insulin)
Diseases named in the same sentence as INS in open-access papers (continued):
Sharing a sentence is not in itself a finding about the gene and the disease.
bladder cancer (40 papers, 2011 to 2026). "Regarding use of T2DM medication, those who used insulin or analogues showed the highest increased risk of invasive bladder cancer HR = 2.65 (95% CI 0.76–9.18), followed by those who used glucose-lowering drugs (excluding insulin) HR = 2.06 (95% CI 1.10–3.65)." (PMID 38492115, 2024). "T2DM participants who used insulin or analogues showed the highest increased risk of invasive bladder cancer, followed by those who used glucose-lowering drugs (excluding insulin)." (PMID 38492115, 2024). "We found an increased risk of invasive bladder cancer in women who used glucose-lowering drugs (excluding insulin) and in men using insulin or analogues." (PMID 38492115, 2024). "Some studies have provided further evidence of a potential risk of bladder cancer associated with insulin." (PMID 34831299, 2021). "On the other hand, the relationship between the use of insulin sensitizing peroxisome proliferator-activated receptor gamma agonists for the treatment of type II DM, such as pioglitazone, and the risk of bladder cancer is still under debate." (PMID 25874217, 2015). "Some in vitro and observational studies provided evidence for a potential risk of bladder cancer associated with insulin use." (PMID 24466131, 2014). "In summary, the present study relieves the concern of a bladder cancer risk associated with the commonly used human insulin." (PMID 24466131, 2014). "Starchy vegetables can raise blood sugar levels faster than non-starchy vegetables, resulting in an increased glycaemic loading and insulin response, and may thereby resist the suggested inverse association between vegetables and bladder cancer." (PMID 33685459, 2021). "The effect of insulin on enhancing GRβ expression and inhibiting GRα suggests that it may increase the risk of bladder cancer." (PMID 27036026, 2016). "Therefore a lack of adjustment for these important risk factors in the age-sex-adjusted models would certainly lead to biased estimates showing a significantly higher risk of bladder cancer associated with insulin use." (PMID 24466131, 2014). "This study relieves the concern of a bladder cancer risk associated with human insulin." (PMID 24466131, 2014). "All of these could exert confounding effects because they are identified risk factors for the outcome of bladder cancer and are also highly correlated with insulin use." (PMID 24466131, 2014). "Notably, T1DM patients also exhibited a heightened risk of bladder cancer, suggesting that the oncogenic potential of insulin therapy may extend beyond T2DM populations." (PMID 39595655, 2024). "Moreover, insulin and rosiglitazone have been reported to potentially influence bladder cancer risks, this likely leads to the incorrect estimation of the association between pioglitazone use and bladder cancer risk." (PMID 29150684, 2017). "Therefore, it is clinically important to clarify whether human insulin is associated with bladder cancer." (PMID 24466131, 2014). "However, because our study was specifically designed to measure the risk of bladder cancer directly related to pioglitazone exposure, the results concerning use of other glucose-lowering therapies (oral or insulin) or other cancer sites should be interpreted with caution." (PMID 22460763, 2012). "Studies have further revealed the plant’s activity against T-24 bladder cancer cells, as well as its potential antidiabetic role in lowering blood glucose levels and elevating insulin." (PMID 37111925, 2023). "Insulin enhances bladder cancer cell growth by activating epidermal growth factor and PI3K pathways." (PMID 34831299, 2021). "This contention is supported by the observation that hypoxia up-regulates IR-expression in bladder cancer, and insulin induces endothelial cell tube formation and migration." (PMID 30989432, 2019). "In contrast to insulin-induced AREG mRNA expression in RT4 bladder cancer cells, PI3K inhibition increased EGF-induced AREG mRNA expression, but not protein secretion." (PMID 27669890, 2016).
bladder cancer (continued). "A cross-talk between insulin and epidermal growth factor has been demonstrated in bladder cancer cell lines." (PMID 24466131, 2014). "Exposure to human insulin and incidences of bladder cancer and hazard ratios comparing exposed to unexposed." (PMID 24466131, 2014). "The following TMUB1-related signalling pathways were identified by GSEA through comparative differential gene analysis: the insulin pathway, bladder cancer, glutathione metabolism, deoxyribonucleic acid (DNA) methylation, signalling by notch, and cell cycle checkpoints." (PMID 38025742, 2023). "Some of them are considered beneficial (metformin and thiazolidinedions—with the exception of bladder cancer); on the other hand, excess of exogenous insulin may be potentially harmful, while other medications seem to have neutral impact on cancer risk." (PMID 33562380, 2021). "In addition, insulin can increase the expression of epidermal growth factors and protein kinase, and induced bladder cancer cell proliferation in in vitro studies." (PMID 31581675, 2019). "Another recent in vitro study suggested that high dose human insulin or insulin glargine may promote bladder cancer cell proliferation via phosphatidylinositol 3-kinases-independent activation of Akt." (PMID 24466131, 2014). "Whether human insulin can induce bladder cancer is rarely studied." (PMID 24466131, 2014). "Although an in vitro study suggested that high dose human insulin may promote bladder cancer cell proliferation, the present study did not support that the use of human insulin in clinical practice in the real world would increase the risk of bladder cancer." (PMID 24466131, 2014). "The results showed that compared with normal tissues, ESR1, PTGS2 and BCL2 in bladder cancer tissues were significantly down-regulated; CASP3, INS, SRC, CDK4, GSK3B and ERBB2 were significantly up-regulated." (PMID 41287122, 2025). "To determine the effect of insulin or dexamethasone (Dex) on GR isoform localization and expression, we treated the T24 and UMUC-3 bladder cancer cells for 30 minutes and labeled with human GRα or GRβ antibodies for immunofluorescence staining." (PMID 27036026, 2016). "Theoretically, a confounder should be correlated simultaneously with both the exposure (insulin use) and the outcome (bladder cancer), and it should not be an intermediate between exposure and outcome." (PMID 24466131, 2014). "The effect of insulin on cancer cell migration rate has not been studied, but the insulin-like growth factor receptor I (IGFR-I) has been shown to promote invasion of bladder cancer cells through an Akt and mitogen activated protein kinase (MAPK) dependent mechanism." (PMID 27036026, 2016).
hypovitaminosis D (40 papers, 2008 to 2026). "For instance, this pathway is responsible for the slower genomic effects of increasing phase 2 insulin secretion in glucose-stimulated insulin secretory responses, thereby linking hypovitaminosis D to relative insulin deficiency." (PMID 38892599, 2024). "Hypovitaminosis D is associated with reduced calcium status in the blood circulation, which ultimately controls insulin synthesis and insulin secretion by beta cells." (PMID 34063822, 2021). "Hypovitaminosis D significantly associated with insulin [R2 = 0.01760, p = 0.0008], HbA1c [R2 = 0.3709, p = <0.0001], and FBG [R2 = 0.3465, p = 0.0001] in only the postmenopausal women." (PMID 29808168, 2018). "During the follow-up, a severe hypovitaminosis D was associated to a worse HbA1c and to higher insulin requirement, but this metabolic effect cannot be explained by an immune role as previously." (PMID 27607348, 2016). "Hypovitaminosis D has been linked to decreased insulin secretion in a diabetic population." (PMID 40806075, 2025). "Vitamin D has been reported to be linked to glucose metabolism as a regulator of insulin secretion and as an enhancer of insulin sensitivity on target tissues, which gives room to the theory that hypovitaminosis D could be incriminated in the onset of IR, and ultimately, of T2DM." (PMID 34445049, 2021). "There are some observational and case-control studies suggesting that hypovitaminosis D is associated with decreased insulin secretion and that vitamin D supplementation reduces the concentrations of free fatty acids in diabetics, thereby improving insulin sensitivity." (PMID 20049157, 2010). "Vitamin D modulates insulin sensitivity and immune function, and hypovitaminosis D is common in T1DM." (PMID 42058333, 2026). "The significance of vitamin D in glucose homeostasis was demonstrated by the enhanced insulin sensitivity observed by the OGIS index 120 minutes after the repair of hypovitaminosis D in prediabetic patients." (PMID 39822434, 2024). "The knocking out of vitamin D receptor and hypovitaminosis D can impair insulin secretion, and treatment of vitamin D can induce insulin-dependent glucose uptake." (PMID 34959910, 2021). "The study results showed that there was an improvement in insulin sensitivity (OGIS index at 120 minutes) after correction of hypovitaminosis D. The improvement in OGIS index was around 4% in the vitamin D group, which is not large enough." (PMID 33457118, 2020). "In older males with hypovitaminosis D, insulin secretion is hyperresponsive to a glucose challenge." (PMID 40806075, 2025). "Overall, these pathways—β-cell dysfunction, reduced insulin sensitivity, and increased inflammatory signaling—offer a comprehensive framework for understanding how early-pregnancy hypovitaminosis D could contribute to the development of GDM." (PMID 41515214, 2025). "The insulin-sensitizing action of vitamin D rather than the distribution volume of this hormone is likely to be responsible for the thigh association between hypovitaminosis D and dismetabolic conditions." (PMID 23935881, 2013). "T2DM patients with hypovitaminosis D displayed significantly increased FBG, insulin, and HOMA-IR compared to normovitaminosis." (PMID 36193546, 2022).
urinary tract infection (40 papers, 2008 to 2025). "Teplizumab, on the other hand, showed promise in reducing C-peptide loss and exogenous insulin requirements and was associated with adverse events such as rash, lymphopenia, urinary tract infection, and cytokine release syndrome." (PMID 38800168, 2024). "Excretion of excess sugar into the urinary tract due to SGLT2i intake raised concerns about the risk of urinary tract infections (UTIs); therefore, this drug was discontinued after hospitalization, while DM was controlled via insulin therapy." (PMID 39135772, 2024). "Another case report also described the development of DKA in a 29-week pregnant patient with normal HbA1c who experienced foetal demise and was managed with fluid replacement, insulin, and antibiotics for a urinary tract infection." (PMID 41556033, 2025). "We present a case of EDKA in a 74-year-old female precipitated by a urinary tract infection which was identified and treated promptly with insulin and dextrose infusion." (PMID 37641775, 2023). "Infections, especially urinary tract infections (11/14; 79% of all infections) and discontinuation of insulin therapy were the two most common precipitating factors." (PMID 38047210, 2023). "There was a slightly significant difference in the occurrence of urinary tract infection between dapagliflozin 10 mg and insulin alone (OR = 0.74, 95% CI: 0.57 to 0.96)." (PMID 35872994, 2022). "Compared with insulin alone, dapagliflozin 5 mg increased the occurrence of urinary tract infection (OR = 1.5, 95% CI: 1.2 to 1.8)." (PMID 35872994, 2022). "Dapagliflozin 5 mg add-on insulin increased the occurrence of urinary tract infection more than placebo add-on insulin." (PMID 35872994, 2022). "DKA is one of the most common and serious hyperglycaemic emergency; and is considered a precipitating event that frequently occurs due to infection [often pneumonia or urinary tract infection], and discontinuation of or inadequate insulin therapy." (PMID 34702335, 2021). "Similar data were reported by a population-based cohort study carried out in Canada which aimed to assess the risk of urinary tract infections and recurrences associated with the initiation of SGLT2 inhibitors in comparison with DPP inhibitors, GLP1-RA, sulfonylureas, thiazolidinediones and insulin." (PMID 40142769, 2025). "The other one was documented to be associated with a urinary tract infection; intensive care unit stay was not required and no insulin pump or Loop system failure was identified." (PMID 36279156, 2022). "However, while varyingly effective in reducing blood glucose and insulin and improving insulin resistance, side effects such as osmotic diarrhea and urinary tract infections curb enthusiasm and widespread use." (PMID 31485454, 2019). "Urinary tract infection was found in 4 patients in metformin groups versus 3 in insulin group." (PMID 27597988, 2016). "The study included about 7400 participants and the results demonstrated that the use of SGLT2 inhibitors did not increase the risk of urinary tract infections or their recurrence compared to other non-insulin medications; moreover, the risk of urinary tract infections was lower compared to insulin." (PMID 40142769, 2025). "Infections, such as pneumonia or urinary tract infections, are common precipitating factors, as they increase insulin requirements and can lead to DKA if not managed appropriately." (PMID 41149081, 2025). "Noncompliance with insulin and concurrent urinary tract infection were the inciting factors." (PMID 38725776, 2024).
adenoma (39 papers, 2009 to 2025). A neoplasm arising from the epithelium. "The levels of IGF-1, the ratio of IGF-1/IGFBP-3, and insulin have been found to be associated with adenomas and advanced adenomas." (PMID 39509387, 2024). "So we conduct this study to explore associations between metformin or insulin use and adenomas risk, the impact of metformin on prevention of secondary adenoma, and to investigate if different treatments affect the risk of adenoma." (PMID 29383018, 2018). "We have previously reported a positive association between elevated fasting plasma insulin levels and adenomas in the Diet and Health Study III." (PMID 22950808, 2012). "Overall, elevated C-peptide or insulin showed a positive association with adenomas (p-trend ≤ 0.01)." (PMID 22950808, 2012). "Individuals with high insulin concentrations also had a higher risk of adenomas (OR = 3.5, 95% CI 1.7-7.4), whereas higher levels of IGFBP-1 were associated with a reduced risk of adenomas in men only (OR = 0.3, 95% CI 0.1-0.7)." (PMID 22950808, 2012). "Little attention has been given to the relationship between insulin-related indicators and adenoma recurrence, and the available literature is controversial." (PMID 38395868, 2024). "Following the removal of the adenoma, the patient's insulin requirement decreased substantially and his blood pressure returned to normal, allowing all blood pressure medications to be discontinued." (PMID 37012937, 2023). "Although the reduction rates were not statistically significant, it is noteworthy that the intake of metformin and metformin in combination with insulin resulted in lower detection rates of adenoma and advanced adenoma among the subjects." (PMID 31831021, 2019). "Insulin and insulin resistance pathways are crucial mediators of the pathophysiology that lead to malignant transition of normal colorectal epithelial cells to adenoma or adenocarcinoma." (PMID 31409045, 2019). "Few epidemiologic studies have explored insulin resistance biomarkers in relation to adenoma recurrence despite insulin’s known mitogenic and anti-apoptotic properties in the colon and exercise responsiveness in other contexts." (PMID 28620703, 2017). "As has been previously observed, pancreatic endocrine pathology is frequently observed in Men1+/− animals, and in our Men1+/− animals was histologically described as adenoma, which were typically immunopositive for insulin." (PMID 22708734, 2012). "Insulin levels and insulin-like growth factor-I are positively associated with CRA incidence, especially advanced adenomas." (PMID 22907422, 2012). "It was also recently demonstrated that serum insulin levels directly correlate with the presence of adenoma and hyperplastic polyps in the proximal colon of humans." (PMID 19627619, 2009). "Finally, we found that patients with unilateral adenomas exhibited significantly higher triglyceride levels and insulin resistance compared to those with bilateral adenomas, suggesting distinct metabolic profiles that warrant further investigation." (PMID 39588423, 2024). "Histological examination after partial resection of the pancreatic head confirmed the diagnosis of insulinomatosis with multifocal microadenomas that were monohormonally positive for insulin and mostly <5 mm in size, except for two larger adenomas (NET G1) of 6 and 7 mm in diameter." (PMID 35406570, 2022). "In a retrospective study involving 339 patients (including T), a decremental trend was observed for adenoma detection rate in groups receiving insulin only, metformin only and insulin and metformin combination (40.9, 33.2 and 32.5%, respectively) although the p value is above 0.05 (p = 0.413)." (PMID 31831021, 2019). "However, using a logistic regression model, subjects having both high insulin level and increased IR-A:IR-B ratio were more likely to have adenomas than individuals with low plasma insulin." (PMID 30453495, 2018).
adenoma (continued). "This risk appears related to a reduced apoptosis of normal rectal mucosa in these subjects and may suggest a role of insulin in the early-phase of the adenoma-carcinoma initiation process." (PMID 30453495, 2018). "In that study, the association of glucose, but not insulin, was most apparent for advanced adenomas." (PMID 22127286, 2012). "All these significant differences in BMI, fasting glucose, insulin levels and HOMA-IR were preserved (p < 0.05) even after the exclusion of the 9 (5.7%) women having adenoma from the hyperprolactinemia group." (PMID 40362476, 2025). "Regarding the metabolic parameters, serum glucose, TG, hemoglobin A1C, and insulin levels were higher, and serum HDL cholesterol levels were lower in the advanced adenoma group than in the control group." (PMID 34242355, 2021). "The insulin secretion AUC and the initial insulin response index were lower than those of the EH group and the nonfunctioning adenoma group." (PMID 34194493, 2021). "The insulin secretion level of the nonfunctional adenoma group showed a downward trend at 30-120 minutes, and the EH group also became gentler than the first 30 minutes." (PMID 34194493, 2021). "In another study, after performing an OGTT and a hyperinsulinemic euglycemic clamp, the authors found that patients with nonfunctioning adenomas were more insulin-resistant than a matched control group and that insulin resistance was related to the tumor size." (PMID 29495350, 2018). "Pituitary NETs were predominantly prolactinomas but somatotrophinomas and nonfunctioning adenomas were also observed, whereas pancreatic NETs predominantly immunostained for insulin." (PMID 26990064, 2016). "During the follow-up period, we observed an increase in fasting blood glucose, fasting insulin, and HOMA-IR in the nonfunctioning adenoma group." (PMID 39050392, 2024).